MYH2 (myosin heavy chain 2)
Description:
Myosins are actin-based motor molecules with ATPase activity essential for muscle contraction.
Synonyms: MyHC-2a; MyHC-IIa; MYHSA2; MYH2A; MYHas8; CMYO6; CMYP6; IBM3
Tractability: PROTAC: ubiquitination databases record sites on it.
Gene: Protein-coding gene on chromosome 17 (10,521,148 to 10,549,700, reverse strand). Ensembl gene ENSG00000125414.
Subcellular location: Cytoplasm, myofibril
Subcellular location (Human Protein Atlas): Focal adhesion sites
Pathways (Reactome):
Disease: FCGR3A-mediated phagocytosis
Immune System: Regulation of actin dynamics for phagocytic cup formation
Gene Ontology:
Molecular function: protein binding; actin filament binding; microfilament motor activity; ATP binding; cytoskeletal motor activity
Biological process: muscle contraction; muscle filament sliding
Cellular component: cell-cell junction; myofibril; protein-containing complex; cytoplasm; cytosol; muscle myosin complex; myosin filament; myosin II complex; sarcomere; myosin complex; supramolecular fiber
Genetic constraint (gnomAD): Loss-of-function variants: 139 observed, 237.9 expected, observed/expected ratio (o/e) 0.58, 90% interval 0.51 to 0.67. The upper end of that interval is the gene's LOEUF score, 0.67, which puts it in group 2 of 6, group 1 being the genes least tolerant of losing a copy. Missense variants: 1,807 observed, 2,450.9 expected, observed/expected ratio (o/e) 0.74, 90% interval 0.71 to 0.77. Synonymous variants: 796 observed, 901.79 expected, observed/expected ratio (o/e) 0.88, 90% interval 0.83 to 0.94.
Gene-disease validity (ClinGen):
ClinGen rates the evidence that MYH2 causes each of these diseases.
myopathy, proximal, and ophthalmoplegia (autosomal recessive): Definitive. Any congenital myopathy in which the cause of the disease is a mutation in MYH2 gene.
myopathy, proximal, and ophthalmoplegia (autosomal dominant): Moderate.
Homologues: Orthologues: chimpanzee MYH2 (99% identical). Paralogues in human: MYH1 (95% identical), MYH8 (93% identical), MYH4 (92% identical), MYH3 (85% identical), MYH13 (82% identical), MYH7 (81% identical), MYH6 (81% identical), MYH7B (68% identical), MYH15 (60% identical), MYH11 (42% identical), MYH9 (41% identical), MYH10 (41% identical), and 32 more.
Diseases named in the same sentence as MYH2 in open-access papers:
MYH2 is named in the same sentence as 63 diseases in open-access papers, as found by Europe PMC text mining. Sharing a sentence is not in itself a finding about the gene and the disease. The quoted sentences say what the papers report.
ophthalmoplegia (5 papers, 2013 to 2023). Weakness or paralysis of at least one of the muscles controlling the movement of the eye. "Among them, MYH2 mutations can cause a class of skeletal muscle diseases characterized by ophthalmoplegia." (PMID 37340028, 2023). "Dominant or recessive mutations affecting the type IIa MyHC (MYH2) are associated with early-onset myopathies with variable muscle weakness and ophthalmoplegia as a consistent finding." (PMID 22918376, 2013). "Additionally, mutations in MYH2 have been associated with dominant myopathy characterized by ophthalmoplegia, congenital joint contractures, and rimmed vacuoles in muscle fibers." (PMID 32315303, 2020). "Moreover, homozygous or compound heterozygous truncating MYH2 mutations cause recessive myopathy with ophthalmoplegia, mild‐to‐moderate muscle weakness, complete lack of type 2A muscle fibers and reduced or absent expression of the corresponding MyHC2 protein." (PMID 32307885, 2020).
congenital myopathies (4 papers, 2020 to 2025). "Taken together, our findings demonstrate a clear pathogenic effect of MYH7 and MYH2 mutations (associated with congenital myopathies) on myosin coiled coil structures." (PMID 37788100, 2023). "Autosomal dominant or recessive pathogenic variants in MYH2 lead to congenital myopathy clinically featured by ophthalmoparesis and predominantly proximal weakness." (PMID 33926564, 2021). "MYH2 mutations are associated with autosomal dominant or recessive congenital myopathies." (PMID 32307885, 2020). "Whereas the atrophy or hypotrophy of type I fibres is a common feature in CM, the marked smallness of type II fibres observed in MYL1‐congenital myopathy rarely occurs in genetic myopathies, specifically in MYH2‐related ones." (PMID 40488356, 2025).
head and neck squamous cell carcinoma (3 papers, 2020 to 2025). A squamous cell carcinoma that arises from any of the following anatomic sites: lip and oral cavity, nasal cavity, paranasal sinuses, pharynx, larynx, and salivary glands. "On the contrary, the expression of MYH2 had the most obvious downregulation, which was proved as a marker in distinguishing head and neck squamous cell carcinoma and lung squamous cell carcinoma." (PMID 40552117, 2025). "MYH2 was proved as a marker in distinguishing head and neck squamous cell carcinoma and lung squamous cell carcinoma." (PMID 37679666, 2023).
arthrogryposis (2 papers, 2016 to 2022). A rare, non-progressive congenital disorder characterized by multiple joint contractures which are present at birth. "Muscle contractures have been reported in early-onset MYH2-associated myopathy and in embryonic myosin heavy chain mutations associated with arthrogryposis." (PMID 27519903, 2016). "However, in the Angus cattle, although there were genes involved in inflammatory disease (OXT) and microcystic adenoma (SHISAL2B), the main function of DEGs was enriched in arthrogryposis (TNNT3 and TNNI2) and myopathy and myasthenic syndrome (MSTN, MYH2, and SLN)." (PMID 35495650, 2022).
Cachexia (2 papers, 2024 to 2025). Severe weight loss, wasting of muscle, loss of appetite, and general debility related to a chronic disease. "The essential role of MYH2, which encodes myosin heavy chain IIA, in the pathophysiology of myopathies and cachexia has been well-documented in numerous studies." (PMID 40093012, 2025). "In fact, the population of Myh2+ myonuclei representing type IIa was clearly diminished with cachexia, whereas Myh4+ myonuclei (type IIb) were enriched." (PMID 39001644, 2024).
cardiomyopathies (2 papers, 2021 to 2025). "These non-mitochondrial diagnoses included a wide variety of disorders, including developmental disorders with intellectual disability, metabolic disorders, epileptic encephalopathies, Bardet-Biedl syndrome, cardiomyopathies, MYH2-related myopathy, and amyloidosis." (PMID 34732400, 2021).
hepatocellular carcinoma (2 papers, 2020 to 2021). A malignant tumor that arises from hepatocytes. "Four thousand four hundred seventy-nine potential pathogenic genes (including MYH2, FGF21, and CYP26A1) for hepatocellular carcinoma were integrated, and cointerpretation analysis was performed with a correlated phenotype." (PMID 34651050, 2021). "MYH2 was confirmed significantly changed in hepatocellular carcinoma and highly expressed in the origin of squamous cell carcinoma in the lungs of patients with previous head and neck malignancies." (PMID 32351322, 2020).
Insulin resistance (2 papers, 2017 to 2025). Increased resistance towards insulin, that is, diminished effectiveness of insulin in reducing blood glucose levels. "In NAFLD, the downregulation of MYH2 may be related to disease-specific mechanisms such as insulin resistance and lipid metabolism dysregulation." (PMID 40093012, 2025). "Meta-analysis of data related to RQ1 (“pathological decline associated with obesity, insulin resistance or type 2 diabetes mellitus”) revealed a significant increase in the abundance of fast-twitch myosin heavy chain isoforms (MYH1 and MYH2) in obesity and T2DM." (PMID 29137117, 2017). "Conversely, systemic insulin resistance and inflammation induced by NAFLD may indirectly affect MYH2 expression and skeletal muscle function.The role of MYH2 in muscle metabolism, inflammatory responses, and chronic diseases underscores its potential as a therapeutic target." (PMID 40093012, 2025).
rhabdomyosarcoma (2 papers, 2015 to 2020). A rare aggressive malignant mesenchymal neoplasm arising from skeletal muscle. "Interestingly, in rhabdomyosarcoma samples, MEF2A level positively correlated with myogenin expression, whereas myogenin level also positively correlated with myosin heavy chain 2 (MYH2A), a marker of late differentiation." (PMID 26384300, 2015). "The downregulation of skeletal myosins (MYH1, MYH2, MYH4) by bortezomib is not easily explained, since skeletal myosins are typically markers of rhabdomyosarcoma rather than leiomyosarcoma." (PMID 32117764, 2020).
sarcopenia (2 papers, 2023 to 2024). Progressive decline in muscle mass due to aging which results in decreased functional capacity of muscles. "Consistently with the findings in dystrophic muscle of mdx mice, we found a sharp upregulation of the MYH3/MYH2 ratio in dependent elderly with sarcopenia indicating a shift in myosin isoform expression from the mature to the embryonic form, which recapitulates a feature of DMD." (PMID 38338718, 2024). "Finally, we identified the gene expression of MYH3 and the MYH3/MYH2 ratio as potential biomarkers of sarcopenia worsening." (PMID 38338718, 2024). "Among older dependent individuals with sarcopenia, there was a significant increase in the MYH3/MYH2 ratio, indicating a transcriptional shift in expression from mature to developmental myosin isoforms." (PMID 38338718, 2024).
Sepsis (2 papers, 2017 to 2025). Sepsis is defined as life-threatening organ dysfunction caused by a dysregulated host response to infection. "Because IL-1β treatment leads to decreased Myh2, Myh4, and Myh7 expression in myocytes, reduced muscular MyHC expression during sepsis might be caused by IL-1β." (PMID 28097512, 2017). "Sepsis upregulated the expression of Myh1 in all groups (P < 0.001), whereas only rAAV-shIlk1 mice displayed increased Myh2 mRNA expression (P < 0.05)." (PMID 41385533, 2025). "Whereas sepsis led to a decreased Myh2 and Myh7 expression in muscle of WT, this effect was blunted in Nlrp3 KO." (PMID 28097512, 2017).
skeletal myopathies (2 papers, 2023 to 2025). "In contrast, pathogenic variants in homologous genes such as MYH2, TPM2, and TNNI2 that encode parts of the skeletal muscle sarcomere cause muscle diseases affecting skeletal muscle, such as distal arthrogryposis (DA) syndromes and skeletal myopathies." (PMID 37457373, 2023).
Tremor (2 papers, 2021 to 2024). An unintentional, oscillating to-and-fro muscle movement about a joint axis. "Hand tremor in this case expands the phenotype of MYH2-associated myopathy, enhancing our understanding of tremor origins." (PMID 39372444, 2024).
atherosclerosis (1 paper, 2025). A disease characterized by the build-up of fatty material and calcium deposition in the arterial wall resulting in partial or complete occlusion of the arterial lumen. "Fap appears to have a distinct expression pattern compared to other markers of activated VSMCs (Acta2 and Myh2) and proliferating or inflammatory molecules in mice models of atherosclerosis." (PMID 40278373, 2025).
breast carcinoma (1 paper, 2024). "Furthermore, the discovery of certain proteins (MYH2, MYL1, MYL2, MYH7) and microRNAs (hsa-let-7d-5p) linked to the advancement of breast cancer offers new, prospective biomarkers for diagnosis and therapy, opening the door for innovative therapeutic approaches." (PMID 39656775, 2024). "The PPI study revealed hub proteins such as MYH2 and MYH7, demonstrating the role of cytoskeletal components in breast cancer etiology." (PMID 39656775, 2024).
dilated cardiomyopathy (1 paper, 2018). Cardiomyopathy which is characterized by dilation and contractile dysfunction of the left and right ventricles. "In contrast to the low frequency of mutations in MYH1 and MYH2, more than 500 disease-causing point mutations have been described in MYH7, with the majority producing hypertrophic or dilated cardiomyopathy." (PMID 29510741, 2018).
Duchenne muscular dystrophy (1 paper, 2024). Duchenne muscular dystrophy (DMD) is a neuromuscular disease characterized by rapidly progressive muscle weakness and wasting due to degeneration of skeletal, smooth and cardiac muscle. "Hence, drawing from the observations made in Duchenne muscular dystrophy, we analyzed the expression of MYH3 in our patients and found a pronounced upregulation in sarcopenic muscle from DP, together with a downregulation of the adult myosin isoform MYH2." (PMID 38338718, 2024).
gastroparesis (1 paper, 2023). Paralysis of the muscles of the stomach wall resulting in delayed emptying of the gastric contents into the small intestine. "Interestingly, MYH2 and CITED2 are known to be dysregulated in T2D, indicating that, unless the patients suffer from gastroparesis, the underlying diabetic condition does not show differences in gene expression patterns in gastric body biopsies." (PMID 37218990, 2023).
glomerulosclerosis (1 paper, 2013). A hardening of the kidney glomerulus caused by scarring of the blood vessels. "We previously reported that podocyte-specific deletion of Myh9 (conventional myosin heavy chain 2A) in C57BL/6 mice does not cause spontaneous kidney disease but instead results in a predisposition to glomerulosclerosis in response to a second model of glomerular injury." (PMID 23874454, 2013).
Hand tremor (1 paper, 2024). An unintentional, oscillating to-and-fro muscle movement affecting the hand. "Our case expands the clinical and mutational spectrum of MYH2-related myopathy and highlights that hand tremor, while rare, is a clinical feature that should not be overlooked in this disease." (PMID 39372444, 2024). "Although hand tremor is not a common clinical feature of MYH2-associated myopathy, it has been reported in patients with four distinct MYH2 gene mutations, encompassing both recessive and dominant types." (PMID 39372444, 2024).
hereditary spastic paraplegia (1 paper, 2021). Hereditary spastic paraplegias (HSP) comprise a genetically and clinically heterogeneous group of neurodegenerative disorders characterized by progressive spasticity and hyperreflexia of the lower limbs. "The pathogenic variants in KIF5A and MYH2 genes are associated with autosomal dominant conditions but not one (hereditary spastic paraplegia or body myopathy type 3) is clinically consistent with symptoms of the patient." (PMID 34439639, 2021).
melanoma (1 paper, 2020). A malignant, usually aggressive tumor composed of atypical, neoplastic melanocytes. "Next, we validated the highest significantly down- (Myh2, Mybh, Sypl2, Xirp1, Mybpc1) and up- (Fcgbp, Areg) regulated genes, including the melanoma-specific genes (Dmnt1 and Nrp2) identified by RNA sequencing following treatment with SAM+anti-PD-1 by RT-qPCR." (PMID 32983966, 2020).
muscle disorders (1 paper, 2023). "Recently, a patient with a homozygous mutation presented a dominant phenotype of rare muscle disorders, while MYH2 (Myosin heavy chain 2) mutations were responsible for autosomal dominant progressive myopathy." (PMID 37691828, 2023).
viral myocarditis (1 paper, 2019). Myocarditis that is caused by an infection with a viral agent. "The viral myocarditis pathway was the only significantly enriched pathway that was distinct to SF; with associated genes falling in the myosin family (Myh2, Myh3, Myh10 and Myh7b)." (PMID 31253821, 2019).
vitamin D deficiency (1 paper, 2017). A nutritional condition produced by a deficiency of VITAMIN D in the diet, insufficient production of vitamin D in the skin, inadequate absorption of vitamin D from the diet, or abnormal conversion of vitamin D to its bioactive metabolites. "Serum vitamin D was positively correlated with MYH2, which is expressed in the fast type II muscle fibers that are preferentially lost in severe vitamin D deficiency." (PMID 28199350, 2017).
myopathy (21 papers, 2008 to 2025). A disease of the muscle in which the muscle fibers do not function properly. "Herein, we describe a male patient with MYH2-associated myopathy who exhibited high-frequency, postural tremor that was notably pronounced in his fingers and appeared in conjunction with muscle weakness and ophthalmoplegia." (PMID 39372444, 2024). "Given that the patient’s parents showed no symptoms of muscle weakness or tremor, and the genetic testing results were consistent with the principle of co-segregation, the patient was diagnosed with autosomal recessive MYH2-associated myopathy." (PMID 39372444, 2024). "This insight underscores the importance of a comprehensive clinical evaluation and suggests that future research should focus on the under-recognized manifestations of MYH2-associated myopathy to improve early diagnosis and treatment strategies." (PMID 39372444, 2024). "We have now identified an additional family with myopathy due to a heterozygous splice-site variant in MYH2, which segregated with the muscle disease in the family." (PMID 36380287, 2022). "Myopathy associated with recessive MYH2 variants is rare but more frequent than the dominantly inherited myosin IIa myopathy." (PMID 36380287, 2022). "The first patients with recessive myosin IIa myopathy carried compound heterozygous or homozygous truncating variants in MYH2." (PMID 36380287, 2022). "Myosin IIa myopathies are autosomal dominant or recessive disorders, caused by variants in the MYH2 gene that encodes the fast IIa myosin heavy chain." (PMID 36380287, 2022). "Whereas recessive MyHC IIa myopathy has been described in many cases, myopathy caused by dominant MYH2 variants is rare and has been described with clinical manifestations and muscle pathology in only one family and two sporadic cases." (PMID 36380287, 2022). "In this study, our aim is to highlight the novel myopathological findings of a patient with MYH2-myopathy culminating in MyHC-IIA protein expression loss, filamentous tangles and clusters of nemaline rods." (PMID 33926564, 2021). "The first pure skeletal myopathy associated with an identified MyHC mutation was a MyHC IIa myopathy, associated with a dominant MYH2 mutation that was described in 2000." (PMID 22918376, 2013). "Three additional mutations in the MYH2 gene have later been identified with myopathies in three families." (PMID 19325803, 2008). "Dominantly inherited myosin IIa myopathy appears to be very rare and was first identified in a large Swedish pedigree with numerous affected individuals and associated with a heterozygous missense variant in MYH2." (PMID 36380287, 2022). "MYH2-myopathy is pathologically characterized by loss and atrophy of type 2A fibers." (PMID 33926564, 2021). "The absence of MyHC IIa may support loss-of-function effects of the homozygous MYH2 missense mutation p.Thr178Ile in patients with recessive myosin IIa myopathy." (PMID 26544689, 2015). "Dominant as well as recessive mutations in MYH2 that cause myopathy have been identified." (PMID 22918376, 2013). "This myopathy, also called “Autosomal dominant MyHC IIa myopathy” (OMIM #605637), is associated with a missense mutation in the MyHC IIa gene (MYH2)." (PMID 19325803, 2008). "HIBM with congenital joint contractures, ophthalmoplegia and rimmed vacuoles is a slowly or non-progressive disease with mild myopathy linked to a mutation in the myosin heavy chain IIa (MYH2) gene that encodes a protein that functions in skeletal muscle contraction." (PMID 36399165, 2023). "Other genes have additionally been reported to play important roles in skeletal muscle developments such as MYH2, MYH7 and MYH8 where myosin myopathies involving these genes have been widely reported." (PMID 32315303, 2020).
myopathy (continued). "Similarly, immunoblot analysis of skeletal muscle tissue from the patient with recessive myosin IIa myopathy, associated with the MYH2 mutation p.Thr178Ile and total absence of MyHC IIa, revealed a roughly 4-fold increased expression of MuRF1 relative to the controls." (PMID 26544689, 2015). "Regardless of the genotype and pattern of inheritance, MYH2-myopathy often manifests also with ophthalmoparesis, as a likely consequence of the high proportion of type 2A muscle fibers within extraocular muscles." (PMID 33926564, 2021).